SOX9 (SRY-box transcription factor 9)
Diseases named in the same sentence as SOX9 in open-access papers (continued):
Sharing a sentence is not in itself a finding about the gene and the disease.
osteosarcoma (continued). "MiR-32 inhibits osteosarcoma cell proliferation and invasion by targeting Sox9, however miR-92a/b as oncogene, promotes cell proliferation and invasion in cancer." (PMID 26036635, 2015). "Another recent study showed that osteosarcoma tissues with high expression of SOX9, a developmental transcription factor, tend to have shorter overall survival and disease-free survival." (PMID 24667142, 2014). "High SOX9 expression was more frequently occurred in osteosarcoma tissues with advanced clinical stage (P = 0.02), positive distant metastasis (P = 0.008) and poor response to chemotherapy (P = 0.02)." (PMID 24188461, 2013). "In the current study, we conducted RT-PCR, Western blot and immunohistochemistry assays to determine the expression patterns of SOX9 at both mRNA and protein levels in osteosarcoma tissues." (PMID 24188461, 2013). "Immunohistochemical staining indicated that SOX9 localized to the nucleus and high SOX9 expression was observed in 120 of 166 (72.3%) osteosarcoma specimens." (PMID 24188461, 2013). "The aim of this study was to investigate the expression pattern and the clinical significance of SOX9 in human osteosarcoma." (PMID 24188461, 2013). "Using Kaplan–Meier method and log-rank test, the overall survival (OS, P < 0.001) and disease-free survival (DFS, P < 0.001) of osteosarcoma tissues with high SOX9 expression were both significantly shorter than those with low SOX9 expression (both P < 0.001)." (PMID 24188461, 2013). "Osteosarcoma patients with high SOX9 expression had shorter overall survival and disease-free survival (both P < 0.001)." (PMID 24188461, 2013). "Interaction between endogenous Exp4 and Sox9 proteins was confirmed in the human osteosarcoma U2OS cells by immunoprecipitation experiments using anti-Sox9 antibody." (PMID 21991335, 2011). "Interestingly, recent studies have also highlighted the potential of targeting Sox9 as a therapeutic strategy for treating osteosarcoma." (PMID 38978960, 2024). "Recent studies have suggested that Sox9 may also play a role in the development and progression of osteosarcoma." (PMID 38978960, 2024). "Additionally, Sox9 is involved in the regulation of the Wnt1 and Fzd1 signaling pathway, which plays a critical role in osteosarcoma cell proliferation." (PMID 38978960, 2024). "Sox9 has been identified as a marker of CSCs in various types of cancer, including osteosarcoma." (PMID 38978960, 2024). "SENP2 produces osteosarcoma inhibitory effects by directly binding and inhibiting Sox9." (PMID 38978960, 2024). "By better understanding the role of Sox9 in osteosarcoma, researchers may be able to develop new and more effective treatments for this type of cancer." (PMID 38978960, 2024). "Furthermore, Sox9 has been identified as a crucial regulator of osteosarcoma stem cells, contributing to the self-renewal, tumorsphere-forming, and tumor-initiating capacities of these cells." (PMID 38978960, 2024). "Overall, these findings suggest that Sox9 plays an important role in the biology of osteosarcoma stem cells and may represent a promising target for developing new treatments for this devastating disease." (PMID 38978960, 2024). "Consequently, patients with high Sox9 expression have shorter overall and disease-free survival rates, highlighting the prognostic value of Sox9 in osteosarcoma." (PMID 38978960, 2024). "MAFB contributes to tumorigenesis and stemness of osteosarcoma by targeting Sox9." (PMID 35333774, 2022). "This study suggests that SENP2 acts as an osteosarcoma suppressor by destabilizing SOX9." (PMID 36078118, 2022). "In addition, studies on osteosarcoma have reported that MAFB increases the expression of stem cell regulatory factor SOX9 at the transcriptional level." (PMID 36248367, 2022). "Of 166 osteosarcoma specimens, 120 (72.3%) highly expressed SOX9." (PMID 24188461, 2013).
osteosarcoma (continued). "In addition, high SOX9 expression was more frequently occurred in osteosarcoma tissues with advanced clinical stage (P = 0.02), positive distant metastasis (P = 0.008) and poor response to chemotherapy (P = 0.02)." (PMID 24188461, 2013). "Similarly, the relative expression levels of SOX9 protein in osteosarcoma tissues (mean ± SD: 2.1 ± 0.4) tended to be significantly higher than that in corresponding noncancerous bone tissues (mean ± SD: 0.6 ± 0.08; P < 0.001)." (PMID 24188461, 2013). "In conclusion, our data show for the first time that SOX9 is upregulated in aggressive osteosarcoma tissues indicating that SOX9 may participate in the tumor progression of osteosarcoma." (PMID 24188461, 2013). "Our data show for the first time that SOX9 is upregulated in aggressive osteosarcoma tissues indicating that SOX9 may participate in the osteosarcoma progression." (PMID 24188461, 2013). "Since it has been demonstrated to be an important regulator of the bone development and chondrocyte phenotype, we hypothesized that SOX9 may be a candidate marker for osteosarcoma progression." (PMID 24188461, 2013). "SOX9 was found to be overexpressed in osteosarcoma that were high grade, metastatic, recurrent, or showed a poor response to therapy, suggesting that it may serve as a marker for osteosarcoma." (PMID 38978960, 2024). "More importantly, SOX9 status is a useful prognostic factor for predicting the prognosis of osteosarcoma, suggesting that SOX9 may contribute to the optimization of clinical treatments for osteosarcoma patients." (PMID 24188461, 2013). "However, very little is known about SOX9 in human osteosarcoma." (PMID 24188461, 2013). "However, it is currently unclear whether the survival of osteosarcoma cells is dependent on SOX9." (PMID 37491298, 2023). "RUNX2 knockdown in SAOS2 reduced SOX9 mRNA and protein levels, and the regulation of SOX9 by RUNX2 is conserved in mouse osteosarcoma cells." (PMID 37491298, 2023). "SUMOylation of SOX9 has been detected in COS-7, chick neural crest cell, U2OS osteosarcoma cells, and 293T cells; however, the consequences of SOX9 SUMOylation varies in these contexts." (PMID 36078118, 2022). "SOX9 knockdown greatly reduces the proliferation and invasiveness of the SENP2 knockout osteosarcoma cells." (PMID 36078118, 2022). "In osteosarcoma cells, THOR increased stemness and migratory capacity via increasing stability of SOX9 mRNA." (PMID 35252166, 2022). "By the way, CD117, IBSP (Stro-1), ID1, SOX9, CD24, CD44 and THBS-1 were also reported to affect osteosarcoma growth and stemness." (PMID 34828292, 2021). "Combining SOX9 and HLA EMR8-5 in a large scale study can probably prove their high prognostic value in osteosarcoma." (PMID 24667142, 2014). "In cancer cells, SENP2 is a potential tumor suppressor because it negatively regulates the proliferation, invasion, and migration of osteosarcoma cells by promoting ubiquitination and degradation of SRY-box-9 (SOX9), a transcription factor required during embryonic development." (PMID 38280996, 2024). "Studies have shown that Sox9 is overexpressed in osteosarcoma tissues compared to noncancerous bone tissues, and its high expression is associated with advanced clinical stages, positive distant metastasis, and poor response to chemotherapy." (PMID 38978960, 2024). "Additionally, melatonin suppresses EMT via the downregulation of SOX9-mediated signaling to inhibit migration and invasion of HOS and U2 cells and decreases tumor initiating cells and lung metastasis of osteosarcoma in the nude mice model." (PMID 31842295, 2019). "Turning to DFS, SOX9 expression (RR 6.1, 95% CI, 1.3-13.9, P < 0.001), clinical stage (RR 1.8, 95% CI, 0.7–8.1, P = 0.03) and metastasis status (RR 2.9, 95% CI, 1.3–10.6, P = 0.02) were also independent prognostic markers for DFS of patients with osteosarcoma." (PMID 24188461, 2013).
osteosarcoma (continued). "The expression levels of SOX9 mRNA were found to be distinctly increased in osteosarcoma tissues compared to noncancerous bone tissues." (PMID 24188461, 2013). "At first, SOX9 was up-regulated in human osteosarcoma tissues compared with noncancerous bone tissues at both mRNA and protein levels." (PMID 24188461, 2013). "SOX9 expression at mRNA and protein levels were both significantly higher in osteosarcoma tissues than those in corresponding noncancerous bone tissues (both P < 0.001)." (PMID 24188461, 2013). "SOX9 mRNA and protein expression levels were detected by RT-PCR and Western blot assays, respectively, using 30 pairs of osteosarcoma and noncancerous bone tissues." (PMID 24188461, 2013).
chondrosarcoma (35 papers, 2007 to 2025). A malignant cartilaginous matrix-producing mesenchymal neoplasm arising from the bone and soft tissue. "Here, we provide results for the first time showing that the loss of SOX9 in chondrosarcoma cells increases the resistance against the oncolytic virus therapy using T-VEC (Talimogen laherparepvec)." (PMID 33076370, 2020). "Since SOX9 is associated with proliferation in various other cell types, we examined the effect of SOX9 inhibition on the growth rate of chondrosarcoma cells." (PMID 33076370, 2020). "The presence of SOX9 peaks associated with these genes in SOX9 ChIP-seq data from rat chondrosarcoma cells is also consistent with direct regulation." (PMID 29659575, 2018). "Therefore, we assumed possible SOX9-independent effects on different MMPs, possibly due to the different additional mutations within the heterogenic population of the chondrosarcoma cell line." (PMID 33076370, 2020). "As the suppression of apoptosis by the acquisition of mutations is considered to be a hallmark of cancer, we concluded that SOX9 drives the accumulation of mutations, genetic and chromosomal modifications and thereby functions as a critical oncogene in chondrosarcoma cancer progression." (PMID 33076370, 2020). "More importantly, SOX9 had been proven to participate in Notch 1 induced cell motility, cell invastion and loss of E-cadherin, and Notch signaling pathway was found participate in cellular differentiation and proliferation in chondrosarcoma." (PMID 26317788, 2015). "Considering our results, we think miR-494 and miR-145 may be correlated with each other to inhibit SOX9 expression in chondrosarcoma cells, but the more specific underlying mechanism should be very complicated and need further research." (PMID 26317788, 2015). "In Chondrosarcoma, low levels of miR-145 lead to the overexpression of SOX9, which in turn activates ETV5, a transcription factor involved in metastasis, ultimately leading to the increased expression of MMP-2 and increased extracellular matrix degradation." (PMID 40429954, 2025). "In chondrosarcoma, SOX9 enhances ETV5 promoter activity when co-transfect ETV5 promoter-reporter plasmid with SOX9 overexpressing lentivirus, but the specific binding sites and interaction mechanism remain to be determined." (PMID 36872348, 2023). "Previous findings suggested that EXT1, EXT2, and Sox9 can be considered genetic markers in the diagnosis and prognosis of chondrosarcoma." (PMID 35760773, 2022). "In line with this, we claim a direct effect of Sox9 on the aggressiveness of chondrosarcoma via MMP13." (PMID 33076370, 2020). "SOX9 expression was reduced by 36.6% in IL-1β-treated human chondrosarcoma cell line SW1353 and this downregulation was reversed dose dependently in the 20 μg/mL CZE and 0.4 μg/mL linarin treatments." (PMID 33321982, 2020). "Our observations provide novel insight into the role of SOX9 in chondrosarcoma and provide a new rationale for analyzing and targeting SOX9 as a novel component in the treatment strategy of chondrosarcoma." (PMID 33076370, 2020). "To assess the expression of SOX9 in chondrosarcoma, we performed a meta-analysis using different open source databases." (PMID 33076370, 2020). "As we observed a clear difference in the proliferative behavior in the SOX9 knockout clones compared to the control chondrosarcoma cells, we assumed a potentially different sensitivity to oncolytic virus treatment." (PMID 33076370, 2020). "Thereby, the association between SOX9 and IDH1 highlight the crucial role of SOX9 in chondrosarcoma biology." (PMID 33076370, 2020).
chondrosarcoma (continued). "SOX9 seemed to affect either directly or indirectly the expression and activity of different integrins and matrix-metalloproteinases (MMPs) in chondrosarcoma cells, giving evidence to an involvement into metastatic potential." (PMID 33076370, 2020). "SOX9 was frequently overexpressed in poorly differentiated chondrosarcomas and SOX9 knockdown suppressed growth of chondrosarcoma cells." (PMID 32759728, 2020). "The results indicated that SOX9 is essential for maintaining proliferation and also the clonogenicity of chondrosarcoma cells." (PMID 33076370, 2020). "We evaluated the effect of reduced and depleted SOX9 expression on the cell cycle of synchronized chondrosarcoma cells." (PMID 33076370, 2020). "Our study shows an increase in SOX9 expression in chondrosarcoma compared to normal cartilage, but a decrease when the tumors are finally defined as dedifferentiated chondrosarcoma (DDCS)." (PMID 33076370, 2020). "Further, to explore the protective efficacy of LI13019F1, we tested the modulation of SOX-9 expression in IL-1β-induced SW1353 human chondrosarcoma cells." (PMID 32565872, 2020). "On average, 1, 2.5, and 5 μg/mL doses of LI13019F1 protected 34.62, 47.66, and 62.29% SW1353 human chondrosarcoma cells from IL-1β induced SOX-9 depletion, respectively." (PMID 32565872, 2020). "The objectives of our research study were to determine the expression pattern of SOX9 in chondrosarcoma biopsies from different grades and thus to understand the role of SOX9 during the process of chondrosarcoma development, progression and dedifferentiation." (PMID 33076370, 2020). "To date, only very few studies have been published on the detailed role of SOX9 during chondrosarcoma development and progression." (PMID 33076370, 2020). "CRISPR/Cas9-mediated knockout of SOX9 in a human chondrosarcoma cell line (HTB94) results in reduced proliferation, clonogenicity and migration, accompanied by an inability to activate MMP13." (PMID 33076370, 2020). "Human conventional chondrosarcomas of all grades express SOX9, which is the main mediator of chondrogenesis." (PMID 29361725, 2018). "MiR-145, which negatively regulates SOX9, was downregulated in human chondrosarcomas, enhancing the relative abundance of SOX9 protein." (PMID 29361725, 2018). "Conversely, knockdown of SOX9 provides inhibition of chondrosarcoma growth and migration, and induces apoptosis and cell cycle arrest." (PMID 29348895, 2017). "Conversely, knockdown of SOX9 suppresses chondrosarcoma growth and migration, and induces apoptosis, cell cycle arrest as well as decreased expression of cancer stem cell markers." (PMID 29348895, 2017). "In contrast, the chondrogenic master regulator SOX9 was dramatically down-regulated in grade 1 chondrosarcoma." (PMID 29044189, 2017). "The direct targeting of Sox9 by miR-494-3p led to the suppression of cell migration, invasion, as well as tumor growth of chondrosarcoma cells." (PMID 29100291, 2017). "The differential expression pattern of SOX9 was confirmed at the protein level by IHC, that its strong expression was detected in enchondromas whereas it was diminished in chondrosarcomas." (PMID 29044189, 2017). "We also found the downstream genes of SOX9 were also significantly down-regulated in chondrosarcoma cells transfected with miR-494 mimics (P < 0.05)." (PMID 26317788, 2015). "In order to further determine the clinical significance of miR-494 in chondrosarcoma, we also split the 71 patients into two groups based on miR-494 or SOX9 expression levels (low vs high) with their mean expression levels as a cutoff point." (PMID 26317788, 2015). "Then we explored the functional role of SOX9 in chondrosarcoma cells, the efficiency of SOX9 siRNA was confirmed by qRT-PCR." (PMID 26317788, 2015). "In the same study, we were able to determine that the transcription factor SOX9 transactivates AP-2ε expression in human SW1353 chondrosarcoma cells." (PMID 26273614, 2015).